TNF (tumor necrosis factor)
Diseases named in the same sentence as TNF in open-access papers (continued):
Sharing a sentence is not in itself a finding about the gene and the disease.
cancer (continued). "The in vitro rhLf-mediated inhibition of cancer proliferation was associated to up-regulation of NF-kβ signaling as well as to the down-regulation of pro-inflammatory and pro-metastatic cytokines, including IL-8, IL-6, granulocyte macrophage colony-stimulating factor and TNF-α." (PMID 32183434, 2020). "The antibody against TNF or soluble TNFR might be used to relieve the pain associated with cancers." (PMID 32434423, 2020). "In normal mucosa, TNF-α mRNA was noted as a few single dots representing very low expression and miR-21 was only occasionally seen in normal mucosa, indicating that the cancer or associated inflammation may be required to induce expression of the two transcripts." (PMID 30999696, 2019). "However, interestingly, the HR was greater for patients with the AA genotype than for those with the GG genotype, suggesting an association between TNF-α-308G>A polymorphism and OS among cancer patients (AA/GG, HR = 2.16, 95% CI: 1.36–3.43, P = .281, I2 = 21.5%)." (PMID 30407345, 2018). "Studies, largely on human cancer cell lines in vitro and in transgenic mouse models, have revealed a complex web of regulatory pathways that integrate the responses of cells to inflammatory cytokines, such as TNF and to pathogen-associated molecular patterns (PAMPs) such as LPS7,12,16,17,21." (PMID 30250197, 2018). "The present study therefore aims to investigate risk factors for ICC and inflammation-linked cancer, and focus on opisthorchiasis and polymorphisms in proinflammatory cytokines (IL-1β and TNF-α) to assess whether these genes are involved in opisthorchiasis-related ICC risk." (PMID 30139338, 2018). "Our data showed that TNF-α -308 G>A polymorphism may be involved in cancer progression." (PMID 28575042, 2017). "Furthermore, GSC could increase the susceptibility of cancer cells to TNFα-triggered cell death via inhibiting NF-κB activity." (PMID 29379440, 2017). "However, the association between the TNF-α 1031T/C polymorphism and cancer risk is controversial." (PMID 28576445, 2017). "Could such systemic and often long-term TNF blockade predispose autoimmune patients to cancer?" (PMID 27148266, 2016). "Therefore, TNF-α T-857C polymorphism may be associated with cancer risk and represents candidate risk marker of cancers." (PMID 28115787, 2016). "CCR4 might be implicated in TNF-α-regulated cancer cells metastasis." (PMID 27356745, 2016). "Particularly with newer biologic agents including TNF blockers, further studies are needed to better determine if there is an increased cancer risk with the therapies themselves, with the higher doses, and longer treatments, or whether any increased cancer risk is due to underlying severe disease." (PMID 26064078, 2015). "Hence, targeting NF-κB may be a rational approach for intervention of inflammation-associated cancers as blocking the TNF-α-NF-κB-FAT10 feedback-loop may result in less side effects." (PMID 26142316, 2015). "In summary, TNF cytokines may play a dual role in the intestine; they have potent proinflammatory activities, but they also function as regulators of apoptosis associated with cancer development." (PMID 24876678, 2014). "Increased expression of COX-2 has been associated with enhanced cell resistance to apoptosis, inflammation, and promotion of tumour progression; therefore this aspect of TNF activity might have relevance to development of IBD-associated cancers of the GI tract." (PMID 25045210, 2014). "In addition, HIV chemotherapy may lead to peripheral neuropathy caused by the massive release of TNF-α in serum and TNF-α therapy for cancer was shown to cause peripheral neuropathy." (PMID 24642694, 2014).
cancer (continued). "We further checked whether the SLA expression on HBx-transfected cells and E-selectin expressed on TNF-α-stimulated endothelial cells is closely associated with cancer cell to endothelial cell interactions for metastatic potential, using antibodies against SLX/A and E-selectin." (PMID 25255877, 2014). "In addition, downregulation of NF-κB in vivo has been shown to increase cancer cell susceptibility to the apoptotic effects of tumor necrosis factor alpha (TNF-α) while also minimizing cell metastatic capability through modulation of growth factors and cytokines." (PMID 23434903, 2013). "Therefore, we determined whether AIMs inhibited NF-03BAB-regulated proteins associated with cancer metastasis; we found that AIMs inhibited the proteins involved in cell proliferation, anti-apoptosis, adhesion, and angiogenesis in the TNF-untreated cells." (PMID 23864892, 2013). "Interestingly, TNFα is also synthesized and secreted from the human endometrial cells and has been associated with physiological and pathological changes in the endometrium-like remodeling, implantation, and cancer." (PMID 24288542, 2013). "Cancer patients exhibit higher serum glucose levels which might be due to the decreased glucose uptake caused by suppression of tyrosine phosphokinase via increased tissue TNF-α." (PMID 24381940, 2013). "We used the data from RABBIT to investigate the frequency of developing a first malignancy in patients treated with anti-TNFα agents compared to those treated with conventional DMARDs and to study the risk of patients with a history of malignancy receiving anti-TNFα therapy." (PMID 20064207, 2010). "In addition, there is sufficient evidence to suggest that remodeling of the immune system with age may also alter cancer risk and consequently alterations in the activity of TNFα may become more pronounced with age." (PMID 18433468, 2008). "TNF-α is a key regulatory factor in cancer cachexia, as its concentration is positively correlated with the degree of weight loss and muscle wasting." (PMID 41526343, 2026). "Cytokine profiling (e.g., IL‐10 and TNF‐α levels) is being explored as a means of monitoring the efficacy of FMT in patients with cancer." (PMID 41496455, 2026). "Herein, we describe the history of the cytokine, the cases in which TNF-α has been considered as a cancer immunotherapy, and the toxicities that can manifest from its use." (PMID 41651411, 2026). "The integrated analysis also revealed a significant enrichment of DEGs in NF-κB, TNF, cancer, IL-17 and MAPK pathways." (PMID 41513624, 2026). "In the current study, we aim to assess the effects of hAMSCs secretome on Panc1 cancer cells via TNF-α/NF-κB signaling pathways." (PMID 41488204, 2026). "Tumor necrosis factor (TNF) exerts paradoxical effects in cancer, driven by the differential engagement of its two receptors, TNFR1 and TNFR2." (PMID 42220483, 2026). "Immunohistochemistry and Western blot for TNF-α expression showed that pro-inflammatory response in bladder was lower in BNCT-IV group among cancer treated groups." (PMID 41998205, 2026). "Notable pathways include TNF signalling pathway (hsa04668), Transcriptional misregulation in cancer (hsa05202), Pathways in cancer (hsa05200) and Cytokine-cytokine receptor interaction (hsa04060)." (PMID 41310336, 2025). "A recent study demonstrated that zebrafish-derived tumor necrosis factor-alpha (TNF-α) can directly induce apoptosis in human cancer cells by engaging their receptors, with macrophages polarized to a pro-inflammatory state driving this effect." (PMID 39940643, 2025). "These CTNF-α-exosomes exhibited enhanced binding to tumor necrosis factor receptor I (TNFR I), thereby promoting TNF-α-mediated apoptosis in cancer cells." (PMID 41254732, 2025). "The stabilized PTEN inhibited the proliferation of ccRCC cells by suppressing the PI3K/AKT and TNF-alpha/NF-kB signaling pathways, and at the same time, enhanced the sensitivity of cancer cells to tyrosine kinase inhibitors (TKIs)." (PMID 41050073, 2025).
cancer (continued). "PA has been reported to activate the intrinsic apoptotic pathway by promoting cytochrome c release from mitochondria, while BV has been shown to enhance apoptosis by targeting TNF-α and disrupting cancer cell membrane integrity." (PMID 40951357, 2025). "TNF inhibitors have the ability to induce cell death in cancer cells, demonstrating significant antitumor effects." (PMID 40507492, 2025). "In cancer, TNF/TNFR1 has been shown to mediate both pro-survival and pro-apoptotic signaling pathways." (PMID 41294802, 2025). "TNF-α can trigger IL-8 release and activate NF-kB transcription factors, crucial elements in cancer progression." (PMID 41398969, 2025). "Here, we have shown that Tob interacts with RIPK1 and NEMO and suppresses TNF-α-induced NF-κB activation by using cancer cell lines." (PMID 40169858, 2025). "After screening with P<0.05, R software was used to perform KEGG pathway enrichment analysis on 11 signaling pathways, including pathways involved in cancer, TNF signaling pathways, and the other pathways." (PMID 40238841, 2025). "Another in-vitro study showed that TNF-α induces cancer metastasis by the generation of MMP, which can change the ECM during metastasis." (PMID 40933989, 2025). "Cancer induces systemic inflammation, mainly via IL-6 and TNF-α, which damages endothelial cells and increases the recruitment of inflammatory cells to atherosclerotic plaques." (PMID 39857281, 2025). "M1 macrophages have anti-cancer and pro-inflammatory effects, such as phagocytosis, lysis, induction of apoptosis via cytokines, tumor necrosis factor (TNF), IL-6, IL-12, and IL-23, and the ability to enhance CD8+ T cells." (PMID 40872475, 2025). "The main inflammatory pathways include IL-17 signaling, the JAK–STAT signaling pathway, the estrogen signaling pathway, and the TNF signaling pathway, along with some related to cancer." (PMID 41487516, 2025). "Notable pathways include the pathways in cancer, TNF signalling pathway and PI3K‐Akt signalling pathway." (PMID 40461955, 2025). "This notion finds support in the elevated levels of inflammatory markers observed in cancer patients, including C-reactive protein (CRP), tumor necrosis factor α (TNF-α), and interleukins 2, 6, and 8, all linked to increased arrhythmic susceptibility." (PMID 41387931, 2025). "In this large cohort, they identified a cumulative cancer incidence of 11.5% (specifically 8.8% in the group treated with anti-TNF agents)." (PMID 40310301, 2025). "Apoptosis, a form of programmed cell death frequently dysregulated in cancer, plays a crucial role in eliminating damaged or abnormal cells and is tightly regulated by various signaling pathways, including the TNF signaling axis." (PMID 40141200, 2025). "Supporting this possibility, some studies have shown that, in cancer patients, the proportion of circulating Tregs positively correlates with serum TNF levels." (PMID 40977146, 2025). "TNFα plays a key role in host immunosurveillance of tumors, mediating the destruction of cancer cells through apoptosis and promoting immune recognition of aberrant cells." (PMID 40282506, 2025). "High IL-10 alongside high IL-6/TNF is sometimes observed in late-stage cancers, indicating a state of chronic inflammatory activation with concurrent immunosuppression." (PMID 41007766, 2025). "TNF-α also varied with histopathological subtype and disease stage, being highest in intestinal-type and advanced-stage cancers." (PMID 40299527, 2025). "Recently, anti-TNFα therapy is being evaluated in other diseases, including coronavirus disease 2019, neuropsychiatric diseases and cancers." (PMID 39856555, 2025). "Tumor necrosis factor-related apoptosis-inducing ligand (TRAIL), a member of the tumor necrosis factor (TNF) family, can specifically induce apoptosis in a variety of cancer cells by binding to pro-apoptotic receptors." (PMID 40683891, 2025).
cancer (continued). "The Schwann cells reciprocate with cancer cells and increase adenosine production with enhanced secretion of IL-6, TNFα and NGF, which ultimately have an augmenting effect on cancer proliferation, migration and invasion." (PMID 40002847, 2025). "The cancer surgery only subgroup analysis included seven studies, and the TNF-α levels was significantly lower in EA cohort (SMD = −0.89, 95% CI = −1.47 to −0.32, I2 = 89%, Egger’s regression p = 0.05, trim and fill reported no missing studies)." (PMID 40427164, 2025). "Based on this evidence, it is clear that TNFα antagonists can generally be used in patients with a history of cancer but that each case should be carefully discussed with oncologists." (PMID 40227584, 2025). "KEGG enrichment analysis further highlighted PELI1-mediated pathways, including PI3K-AKT, MAPK, Wnt and TNF signaling—pathways well-characterized in LIHC for targeted anti-cancer drug development." (PMID 41562077, 2025). "Among the 36 cytokines and chemokines analyzed, YQHXJDD ELNVs significantly upregulated the peripheral blood level of TNF-α, thereby potentiating the cytotoxic activity against malignant tumors." (PMID 41170390, 2025). "The proposed cytotoxic mechanism underlying these α-blockers differed in the various cancers and included VEGF, EGFR/HER2, integrin, TNFα, and other mitochondrial apoptotic-inducing factors." (PMID 41154665, 2025). "IL-2, IL-12, and TNFα are potent pro-inflammatory cytokines that have been identified as promising anti-cancer biopharmaceuticals." (PMID 39773310, 2025). "Taking cues from previously established methods mimicking cancer microenvironment, we triggered cachexia in differentiated myotubes using pro‐inflammatory cytokines TNF‐α and IFN‐γ for 48 h." (PMID 40183240, 2025). "Bioinformatics analysis identified critical candidate genes (Col4a6, Csf2) and pathways (PI3K-Akt, TNF) in inflammation-to-cancer conversion." (PMID 41415031, 2025). "In support of this, broad-spectrum antibiotics in a non-cancer context (obese mice) have been shown to reduce circulating LPS and lower systemic TNF-α/IL-6 levels." (PMID 40572244, 2025). "Interferon- γ (IFN-γ) and tumor-necrosis factor α (TNF-α) concentrations were significantly elevated in the supernatant of BaEV-CAR γδ T cells co-cultured with cancer cells expressing B7H3." (PMID 40547029, 2025). "The study aimed to prospectively investigate the clinical value of interleukin-6, myeloperoxidase, and tumor necrosis factor alpha as potential biomarkers of cancer therapy-related cardiac dysfunction (CTRCD) in patients receiving anthracycline treatment." (PMID 40362309, 2025). "Kyoto Encyclopedia of Genes and Genomes (KEGG) pathway analysis revealed that these differentially expressed genes were enriched in pathways related to the TNF signaling pathway and the PD-L1/PD-1 checkpoint pathway in cancer." (PMID 40382627, 2025). "We postulated that a nutrient–inflammation interaction score (NIIS), combining circulating TNF-α with the geriatric nutritional risk index (GNRI), would capture this synergistic axis and forecast de-novo cancer in HF." (PMID 41473193, 2025). "Meanwhile, phosphorylated NF-κB (p-p65) were markedly downregulated in LPS-induced cancer cells when treated with nobiletin while TNF-α-induced NF-κB expression was suppressed with upregulation of IκBα." (PMID 39860214, 2025). "Treatments like surgery, chemotherapy, and radiotherapy associated with cancer, alongside psychological stress, can trigger the production of proinflammatory cytokines such as IL‐1, INF‐α, IL‐6, and TNF‐α." (PMID 40387308, 2025). "Elevated circulating inflammatory markers, including C-reactive protein, IL-6, TNF-α, and monocyte chemoattractant protein-1, represent common features of both cardiovascular disease and cancer, reflecting shared systemic inflammatory burden." (PMID 41555998, 2025).
cancer (continued). "By collecting and growing CTCs from patients, this study highlights the importance of certain molecular pathways, such as TNF/NF-kB and hedgehog signaling, in cancer progression and treatment failure." (PMID 39941724, 2025). "Pro-inflammatory cytokines like IL-1, IL-6, and TNF-α are often elevated in cancer, contributing to cancer cachexia and reduced treatment efficacy." (PMID 41387645, 2025). "A recent study demonstrated that the presence of TNF+ or VEGF+ MCs varies across different types of cancer." (PMID 41465542, 2025). "Ongoing trials analyzing TNF antagonists for ameliorating the adverse effects of other cancer therapies will be interesting to follow." (PMID 40004724, 2025). "Studies suggest CD15 facilitates cancer cell adhesion to the brain endothelium, particularly under TNF-α-induced inflammatory conditions." (PMID 39780275, 2025). "Regular exercise reduces circulating pro-inflammatory cytokines such as IL-6 and TNF-α in cancer patients." (PMID 41583457, 2025). "The cytokines associated with the pre-cancer or the initiation stage of HCC, TGF-β, FGF2, IL-8, and TNF-α were expressed at similar levels in the HIV + participants compared to the HCC + participants." (PMID 41219858, 2025). "Both IL-1β and TNFα have been shown to promote cancer progression through cell proliferation, migration, and metastasis." (PMID 40381373, 2025). "In conclusion, the interplay between these inflammatory mediators—IL-6, IL-1β, TNF-α, CCL2, PGE2, GM-CSF, and bradykinin—highlights their collective role in the mechanisms underlying cancer pain." (PMID 40579593, 2025). "For example, LAMP3+ conventional DCs (cDCs) were observed to be widely present in different types of cancer, and greater abundance of TNF+ mast cells was found in NPC." (PMID 40954554, 2025). "They suggest that miR-21 protects cancer cells and fibroblasts from autocrine and paracrine TNF-induced cell death." (PMID 41476448, 2025). "The KEGG pathway analysis suggested that the genes were involved in the IL-17 signaling, TNF signaling, NF-kappa B signaling, transcriptional misregulation in the cancer pathway." (PMID 40510589, 2025). "The inflammatory cytokines secreted by leukocytes, such as TNF-α, IL-6, and IL-1β, promote cancer cell proliferation, survival, and resistance to apoptosis." (PMID 39869563, 2025). "Macrophages and neutrophils primarily contribute to the synthesis of TNFα, which subsequently stimulates the production of other proinflammatory cytokines, including IL-6 and IL-1β, thus promoting cancer." (PMID 40869207, 2025). "4T1 cells were infected with SFV/Luc encoding firefly Luc gene (referred to as SFV or Luc) and two potential immunotherapy virus vectors, SFV/IFNγ and SFV/TNFα, to investigate the possibility of mitigating cancer cell effects on macrophages." (PMID 40547518, 2025). "TNF-α is a pro-inflammatory cytokine, known for its significant involvement in inflammation, apoptosis, and cancer." (PMID 40959697, 2025). "Monocytes and macrophages, the main tumor-infiltrating cells, produce cytokines like IL-1β, IL-6, IL-23, and TNF-α, playing a crucial role in cancer progression within an inflammatory context." (PMID 40430101, 2025). "IL-6 and TNF-alpha are pro-inflammatory cytokines that have been shown to significantly impact various cancer-related biological processes, including cell proliferation, angiogenesis, invasion, and metastasis." (PMID 40558287, 2025). "IL-8, often in concert with other cytokines like TNFα, significantly influences various aspects of cancer biology across multiple cancer types, including melanoma, prostate, colon, breast, lung, and pancreatic cancers." (PMID 41002568, 2025). "Upregulation of the number and activity of CD8+ T cells in OC allows for eradication of ovarian cancer cells through granzymes, IFN-γ and TNF-α secretion after cancer-antigen recognition." (PMID 40136652, 2025).